SMAD4 (SMAD family member 4)
Diseases named in the same sentence as SMAD4 in open-access papers (continued):
Sharing a sentence is not in itself a finding about the gene and the disease.
ovarian carcinoma (continued). "Overexpression of circATRNL1 or knockdown of miR‐378 suppressed angiogenesis and ovarian cancer cell proliferation, invasion, and migration via decreasing proliferation‐ and migration‐related proteins via miR‐378 or Smad4, respectively." (PMID 33372356, 2021). "In conclusion, miR-30a mediates DDP resistance in ovarian cancer by inhibiting autophagy via the TGF-β/Smad4 pathway." (PMID 34747309, 2021). "In summary, with a combination of in vitro and in vivo methods, we show that circATRNL1 plays an essential role in ovarian cancer and functions to suppress cancer metastasis and angiogenesis via targeting miR‐378/Smad4." (PMID 33372356, 2021). "In previous studies, we found that the expression of the SMAD4 gene significantly differed in healthy patients compared to those with ovarian cancer." (PMID 34205023, 2021). "circATRNL1 suppressed ovarian cancer cell proliferation, migration, invasion, and angiogenesis via miR‐378/Smad4." (PMID 33372356, 2021). "We then investigated the role of circATRNL1/miR‐378/Smad4 in ovarian cancer in vivo using nude mice intraperitoneal xenograft." (PMID 33372356, 2021). "In vitro studies on cell lines demonstrated that the increased expression of SMAD4 inhibits the migration and proliferation of ovarian cancer cells." (PMID 34205023, 2021). "We, therefore, conclude that circATRNL1 regulates ovarian cancer cell proliferation, migration, invasion, and angiogenesis through Smad4." (PMID 33372356, 2021). "We have showed that circATRNL1 regulated ovarian cancer cell proliferation and migration via binding to miR‐378 and that miR‐378 modulated cancer cell proliferation and migration through targeting Smad4." (PMID 33372356, 2021). "In the current study, we used ChIP-seq technology to study TGFβ/SMAD4 regulation in the platinum-sensitive A2780 ovarian cancer cell line." (PMID 21799915, 2011). "In conclusion, our data highlight the utility of next generation sequencing technology to identify genome-wide SMAD4 target genes in epithelial ovarian cancer and link aberrant TGFβ/SMAD signaling to ovarian tumorigenesis." (PMID 21799915, 2011). "We have for the first time applied ChIP-seq technology to whole-genome-wide mapping of TGFβ-stimulated, SMAD4-dependent regulated genes in an ovarian cancer cell line (A2780)." (PMID 21799915, 2011). "Here, we elucidated the function of circATRNL1/miR‐378/Smad4 in ovarian cancer." (PMID 33372356, 2021). "In this study, we fully investigated the role of circATRNL1/miR‐378/Smad4 axis in ovarian cancer." (PMID 33372356, 2021). "The authors suggested that SMAD4 may inhibit the invasion and metastases of human ovarian cancer cells through a pathway that is also mediated by TGF-β." (PMID 34205023, 2021). "Up-regulated miR-205 promoted the proliferation of ovarian cancer cells by targeting PTEN/SMAD4." (PMID 33402116, 2021). "We next investigated the role of miR‐378/Smad4 axis in ovarian cancer." (PMID 33372356, 2021). "We study whether microRNA miR-30a inhibits the autophagy through transforming growth factor (TGF)-β/Smad4 to generate cisplatin (DDP) resistance in ovarian cancer cells." (PMID 34747309, 2021). "The important role of circATRNL1/miR‐378/Smad4 suggests that it could serve as a biomarker for ovarian cancer diagnosis or even an avenue for future therapy development." (PMID 33372356, 2021). "Although nude mice experiment indicated the loss of SMAD4 did not influence the tumor growth, it inhibited the barrier integrity in endothelial cell and promoted the ovarian cancer liver metastases." (PMID 33102229, 2020). "However, it was found that miR-205 regulated the proliferation and invasion of ovarian cancer OVCAR-3 cell line via suppressing PTEN/SMAD4 expression." (PMID 30510566, 2018).
ovarian carcinoma (continued). "Our focused analysis of TCGA ovarian cancer data did not identify mutations in SMAD4; however, we did identify significant dysregulation of key TGF-β/SMAD genes, despite the fact that the vast majority of samples are from primary tumors." (PMID 28060758, 2017). "In ovarian cancers, down-regulated Smad4 was detected in clinical patients specimens, which indicated that Smad4 might enhance TGF-β signaling." (PMID 28145479, 2017). "Moreover, dysregulation of transforming growth factor-β/SMAD4 signaling leads to epigenetic silencing of its downstream target ADAM19 in ovarian cancer cells." (PMID 29138461, 2017). "Especially, the strong different expression of POSTN and SMAD4 from stage III to IV may mark the ovarian cancer metastasis process." (PMID 26486520, 2015). "Mutations in SMAD4 are not very common in ovarian cancer but were reported in primary cultures or cell lines." (PMID 22943793, 2012). "Recently, genome-wide screening done by ChIP-seq of TGF-β-induced SMAD4 binding in epithelial ovarian cancer revealed that SMAD4-dependent regulatory network was strikingly different in ovarian cancer compared to normal cells and was predictive of patients survival." (PMID 22943793, 2012). "Furthermore, based on gene regulatory network analysis, we determined that the TGFβ-induced, SMAD4-dependent regulatory network was strikingly different in ovarian cancer compared to normal cells." (PMID 21799915, 2011). "Overall, our gene regulatory network analysis strongly indicates that TGFβ stimulates a different SMAD4-dependent regulatory mechanism in ovarian cancer cells compared to normal cells, i.e., the SMAD4 regulation network has become “rewired” in ovarian cancer cells." (PMID 21799915, 2011). "In conclusion, our study provides the first comprehensive genome-wide map of thousands of TGFβ/SMAD4 targets in an ovarian cancer cell line, which could further be used for studying SMAD4 functions in tumorigenesis." (PMID 21799915, 2011). "Importantly, the TGFβ/SMAD4 target genes identified in the A2780 epithelial ovarian cancer cell line were predictive of patient survival, based on in silico mining of publically available patient data bases." (PMID 21799915, 2011). "We hypothesized that miR‐378 is involved in ovarian cancer through Smad4 signaling." (PMID 33372356, 2021). "Previous study has proved that Smad4 can regulate the PI3K/AKT pathway to increase autophagy and apoptosis in ovarian carcinoma cell lines." (PMID 38230565, 2024). "SMAD4 is an essential part of TGF-β/SMAD signaling, and mutant SMAD4 ovarian cancer cells decrease PDCD4's expression, which regulates EMT." (PMID 37497408, 2023). "In ovarian cancer, miR-183 regulates cell proliferation and apoptosis by targeting Smad4 (Recombinant Mothers Against Decapentaplegic Homolog 4) through the TGF-β/Smad4 signaling pathway." (PMID 37372440, 2023). "CircATRNL1 absorbs miR-378, activates Smad4, and further decreases the activities of Akt, Cyclin D1, MMP2 and MMP9, thereby inhibiting proliferation, angiogenesis and metastasis of ovarian cancer cells." (PMID 37940982, 2023). "The expression of miR-30a, Smad4, and TGF-β was detected in the serum of ovarian cancer patients and DDP-resistant cell lines (A2780) by quantitative real-time polymerase chain reaction (qRT-PCR)." (PMID 34747309, 2021). "In ovarian cancer, the TGF-β-activated SMAD3/SMAD4 complex is recruited to the promoter region of FXYD5 and promotes FXYD5 transcription." (PMID 34270462, 2021). "In ovarian cancer, SMAD3 acts alone or in conjunction with SMAD4 to regulate transcription of EMT target genes." (PMID 28060758, 2017). "Overall, we suggest that miR-205 functions as an oncogenic miRNA by directly binding to SMAD4 and PTEN, providing a novel target for the molecular treatment of ovarian cancer." (PMID 28145479, 2017).
ovarian carcinoma (continued). "Indeed, GO analysis for SMAD4 target genes without gene expression level changes after TGFβ stimulation found one of the enriched gene categories is ‘EGF like signaling’, providing further evidence that other signaling pathways may modulate SMAD4-dependent regulated genes in ovarian cancer." (PMID 21799915, 2011). "Interestingly, this miRNA was also found as a regulatory element for genes such as PTEN, SMAD4, ESR1, NRG1, etc., in the miRWalk database for ovarian carcinoma." (PMID 36899893, 2023). "Our candidates also included several genes typically considered TSGs, including CDKN1A (bladder carcinoma, 9.2% in TCGA), KMT2A (kidney carcinoma, 0.6%), MGA (ovarian carcinoma, 1.5%), PTEN (high-grade glioma, 14.2%), RB1 (lung adenocarcinoma, 5.0%), SMAD4 (ovarian carcinoma, 0.5%)." (PMID 34313788, 2021). "In ovarian cancer, FoxO3a interacted with a SMAD2/SMAD3/SMAD4 complex in the nucleus, which could maintain activated SMAD proteins at high levels, and this interaction in turn promoted the cell-cycle arrest synergistically." (PMID 31640193, 2019). "MiR-183 is highly expressed in ovarian cancer cells and down-regulation of miR-183 markedly represses cell proliferation and promotes apoptosis via targeting SMAD family member 4 (Smad4)." (PMID 31803223, 2019). "For example, it was recently shown that BMP9 acts as a proliferative factor in ovarian surface epithelial cells and ovarian cancer cell lines via signaling through Alk2/Smad4 pathway, rather than through Alk1." (PMID 22457812, 2012). "It has been suggested that SMAD4 and SMAD3 are involved in metastatic potential of ovarian cancers." (PMID 22943793, 2012). "Furthermore, the function of miR-205 in ovarian cancer may be exerted via downregulation of the target genes SMAD4 and PTEN, which play an important role in the function of miR-205 in ovarian cancer." (PMID 28145479, 2017).
pancreatic adenocarcinoma (48 papers, 2007 to 2026). "As demonstrated in pancreatic adenocarcinoma, the loss of tumor suppressor SMAD4/DPC4 has been identified in BilN and IPNB precursor lesions and has been implicated in carcinogenesis." (PMID 38201457, 2023). "When repeating the analysis with pancreatic adenocarcinoma (PAAD) samples that also frequently show SMAD4 mutations, a similar random distribution was observed." (PMID 34857888, 2022). "SMAD4 mutations are important, particularly in pancreatic carcinogenesis, where they have been found in roughly 50% of pancreatic adenocarcinoma and 20% of invasive ampullary carcinoma." (PMID 35778698, 2022). "Prognosis in pancreatic adenocarcinoma (PDA) is worsened by loss of the tumor suppressor gene SMAD4." (PMID 34002944, 2021). "It was found that SMAD4 gene inactivation, by intragenic mutation or homozygous deletion, leads to poor prognosis for patients with surgically resected pancreatic adenocarcinoma." (PMID 32429474, 2020). "The inactivation of SMAD4 signaling is also associated with poorer prognosis in patients with adenocarcinoma of the pancreas and cancers of the esophagus." (PMID 31867281, 2019). "Prospective studies will be needed to provide a more rigorous analysis of the role of SBRT fractionation in pancreatic adenocarcinoma as well as the possible contribution of SMAD4 mutation status and evolving systemic therapy on LC." (PMID 29184848, 2017). "Among these, Smad4 mutation is relatively specific and its inactivation is found in more than 50% of invasive pancreatic adenocarcinomas." (PMID 28067794, 2017). "The role of Smad4 gene as an important tumor suppressor gene came out by the novel study of the allelotype loss in pancreatic adenocarcinoma." (PMID 20565773, 2010). "In addition, we expanded our study to other SMAD4-deficient pancreatic adenocarcinoma cell lines such as CFPAC-1 and BxPC-3 cells." (PMID 35151689, 2022). "SMAD4 inactivating mutations are common in gastric, colorectal, and pancreatic adenocarcinomas, whereas up to 20% of head and neck, bladder, cervical, and lung squamous carcinomas contain inactivating mutations in TGFβ signaling components like SMAD2, SMAD3, SMAD4, TβR1, or TβRII." (PMID 33418880, 2021). "Overall inactivation or loss or Smad4 is found in about 60%–90% of pancreatic adenocarcinomas." (PMID 28067794, 2017). "Other genes often mutated in subclones are the splicing factor SF3B1 and, in breast and pancreatic adenocarcinomas, the tumor suppressor SMAD4." (PMID 33831375, 2021). "We showed a correlation between the genetic status of SMAD4 and the expression levels of Sonic hedgehog pathway proteins in patients with pancreatic adenocarcinoma." (PMID 31417657, 2019).
pancreatic adenocarcinoma (continued). "Suppressing Smad4 through specific RNAi upregulates ALDH1A1 mRNA expression whereas Smad4 overexpression downregulates ALDH1A1 mRNA expression in pancreatic adenocarcinoma cells." (PMID 30733805, 2019). "In pancreatic adenocarcinoma, this tumor suppressive action is often lost by the inactivation of Smad4-dependent TGF-β signaling." (PMID 28067794, 2017). "In this review, we will discuss the molecular mechanism of TGF-β/Smad4 signaling in the pathogenesis of pancreatic adenocarcinoma and its clinical implication, particularly potential as a prognostic factor and a therapeutic target." (PMID 28067794, 2017). "DPC4/SMAD4 is inactivated in 50% of pancreatic adenocarcinomas in humans by homozygous deletions (30%) or intragenic mutations in one allele coupled with loss of heterozygosity (LOH) (20%)." (PMID 24212630, 2011). "Pancreatic adenocarcinoma showed positive immunohistochemical staining for SMAD4 in 80%, CK19 in 100% and CA19-9 in 100% of the selected cases." (PMID 17587453, 2007). "Taken together, these studies suggest that SMAD4 expression is highly useful in diagnosing pancreatic adenocarcinoma." (PMID 17587453, 2007). "Twenty-five selected cases of clinically confirmed pancreatic adenocarcinoma were evaluated for all three markers, of which 80% of the cases stained positive for SMAD4, while 100% of the cases were positive for CK19 and CA19-9." (PMID 17587453, 2007). "SMAD4, CK 19 and CA 19-9 immunoreactivity in non-pancreatic adenocarcinoma is highlighted in this table." (PMID 17587453, 2007). "In our own study, 18 of the 20 patients with SMAD4 positivity died within 6 months of diagnosis and 2 (low positivity SMAD4 expression) of the 20 patients were still alive 7 and 9 months after diagnosis of pancreatic adenocarcinoma." (PMID 17587453, 2007). "Additionally, similar results were obtained from the profiling of mutations in SMAD4 and CDKN2A, which are frequently observed in patients with regular pancreatic adenocarcinoma." (PMID 39651731, 2024). "SMAD4, a tumor suppressor gene, is lost in up to 60%–90% of pancreatic adenocarcinomas (PDAs)." (PMID 34002944, 2021). "As the tumor develops, the SMAD4/DPC4 gene is frequently altered, which is an indicator of poor prognosis in pancreatic adenocarcinoma." (PMID 29463243, 2018). "This study also showed that in addition to SMAD4 and CK19, CA19-9 was also useful for confirming the diagnosis of pancreatic adenocarcinoma." (PMID 17587453, 2007). "Our study has demonstrated that the immunohistochemical staining panel of SMAD4, CK19, and CA19-9 is useful in confirming the diagnosis of pancreatic adenocarcinoma." (PMID 17587453, 2007). "However, the tumor suppressive function is often lost in pancreatic adenocarcinoma by inactivation of the TGF-β signaling mediator, Smad4." (PMID 28067794, 2017).
pancreatic adenocarcinoma (continued). "In the control group comprising of non-pancreatic adenocarcinoma SMAD4 was negative (100%) in all 10 cases of colonic and pulmonary adenocarcinoma." (PMID 17587453, 2007). "The 5 patients who were negative for SMAD4 expression died between 11 and 13 months after diagnosis of pancreatic adenocarcinoma." (PMID 17587453, 2007). "In addition, based on data from colorectal and pancreatic adenocarcinoma cell lines, it has been shown that S100A9 is preponderant in the promotion of tumor growth in SMAD4-negative cancer cells supporting a link between S100A9/TGF-β/SMAD4." (PMID 34201758, 2021).